ZNF425 (zinc finger protein 425)
Description:
Acts as a transcriptional repressor.
Tractability: No criterion of Open Targets' tractability assessment is met for any kind of drug.
Gene: Protein-coding gene on chromosome 7 (149,102,784 to 149,126,338, reverse strand). Ensembl gene ENSG00000204947.
Subcellular location: Nucleus; Cytoplasm
Subcellular location (Human Protein Atlas): Nucleoplasm
Pathways (Reactome):
Gene expression (Transcription): Generic Transcription Pathway; Regulation of endogenous retroelements by KRAB-ZFP proteins
Gene Ontology:
Molecular function: protein binding; DNA-binding transcription factor activity, RNA polymerase II-specific; RNA polymerase II transcription regulatory region sequence-specific DNA binding
Biological process: negative regulation of DNA-templated transcription; regulation of transcription by RNA polymerase II; regulation of DNA-templated transcription
Cellular component: cytoplasm; nucleoplasm; nucleus
Genetic constraint (gnomAD): Loss-of-function variants: 17 observed, 15.99 expected, observed/expected ratio (o/e) 1.06, 90% interval 0.73 to 1.59. The upper end of that interval is the gene's LOEUF score, 1.59, which puts it in group 6 of 6, group 1 being the genes least tolerant of losing a copy. Missense variants: 714 observed, 832.34 expected, observed/expected ratio (o/e) 0.86, 90% interval 0.81 to 0.91. Synonymous variants: 369 observed, 331.92 expected, observed/expected ratio (o/e) 1.11, 90% interval 1.02 to 1.21.
Homologues: Orthologues: chimpanzee ZNF425 (99% identical), macaque ZNF425 (96% identical), Drosophila melanogaster CG3281 (16% identical), Drosophila melanogaster CG2712 (16% identical), Drosophila melanogaster Phs (15% identical). Paralogues in human: ZNF133 (30% identical), ZNF264 (28% identical), ZNF875 (28% identical), ZNF805 (28% identical), ZNF599 (28% identical), ZNF337 (27% identical), ZNF169 (26% identical), ZNF749 (26% identical), ZNF266 (25% identical), ZFP90 (25% identical), ZFP37 (25% identical), ZNF614 (24% identical), and 50 more.